EGFR (epidermal growth factor receptor)
Diseases named in the same sentence as EGFR in open-access papers (continued):
Sharing a sentence is not in itself a finding about the gene and the disease.
cancer (continued). "EGFR activity, which was more accurately predicted by the ratio of Mig6/EGFR, highly correlated with erlotinib sensitivity in panels of cancer cell lines of different tissue origins." (PMID 23935914, 2013). "Using the epidermal growth factor receptor, a key cancer target molecule, we demonstrate ∼10 nm resolution while continuously covering the range of ∼10–80 nm." (PMID 23650512, 2013). "Both Cetuximab and the SM TKIs have been shown to have significant antitumor activity in various EGFR over-expressing cancers, and to enhance the potency of chemotherapy or radiotherapy in various pre-clinical and early phase I or II clinical studies." (PMID 24252457, 2013). "Decreased activity of EGFR leads to downregulation of these signaling cascades resulting in apoptosis of cancer cells." (PMID 23555785, 2013). "In humans, EGFR is frequently overexpressed in 50–81% of NSCLC and such overexpression has been demonstrated to be associated with cancer susceptibility, metastasis, survival prognosis and chemotherapy response." (PMID 24137392, 2013). "Epidermal Growth Factor (EGF) plays an important function in the regulation of cell growth, proliferation, and differentiation by binding to its receptor (EGFR) and providing cancer cells with increased survival responsiveness." (PMID 23724959, 2013). "PTPN12 has recently been shown to be downregulated in some cancers, leading to hyperactivity of RTKs (EGFR and MET) and hypersensitivity to TKIs that inhibit these kinases." (PMID 24189400, 2013). "Studies investigating the signaling pathways that promote the growth and spread of cancer cells suggest that the information transmitted by means of TGFα-EGFR signaling is particularly important for progression of tumors that develop in the colon." (PMID 23986907, 2013). "Reports also indicate that EGFR regulates the constitutive activation of NF-κB in different cancer cells." (PMID 24340014, 2013). "We found that EGFR-TKI treatment in cancer cells increased IL-6 secretion, even if EGFR phosphorylation was completely blocked by EGFR-TKI." (PMID 23592411, 2013). "The utilization of monoclonal antibodies conjugated to gold nanoparticles has proven to be effective in targeting cancer cells with an over expression of EGFR (epidermal growth factor receptor)." (PMID 23483913, 2013). "Over the past several decades, many studies on EGFR-targeted therapy in cancer have been performed and numerous targets for anticancer agents have emerged." (PMID 23706036, 2013). "It is widely accepted that EGF, vascular endothelial growth factor, bFGF and EGFR are correlated with cancer cell growth." (PMID 23946783, 2013). "Below we focus on the regulation of EGFR signal networks by miRs in cancer and the involvement of miRs in facilitating resistance to EGFR-inhibition." (PMID 24349829, 2013). "The use of anti-cancer target agents is increasing, such as the anti-cancer target drugs blocking the EGF/EGFR system." (PMID 24127898, 2013). "Epidermal growth factor receptors (EGFR) are a large family of receptor tyrosine kinases which are overexpressed in many types of cancer, including breast, lung, esophageal, and head and neck." (PMID 24312376, 2013). "The epidermal growth factor receptor (EGFR) regulates normal growth and differentiation, but dysregulation of the receptor or one of the EGFR ligands is involved in the pathogenesis of many cancers." (PMID 23472148, 2013). "Cancers are often associated with deregulation of RTK activity, and these receptors, such as Epidermal Growth Factor receptor HER-2, c-Kit or VEGF-R, constitute pertinent chemotherapeutical targets in diverse anti-cancer therapies." (PMID 23696913, 2013). "These cancers exhibit sensitivities to EGFR tyrosine kinase inhibitors (TKIs), such as gefitinib or erlotinib, supporting the use of these drugs for effective treatment of NSCLC." (PMID 23341890, 2013).
cancer (continued). "Anticancer therapeutics that specifically target the well-defined signaling pathways important for cancer cell proliferation, invasion and metastasis such as EGFR or VEGFR pathway have shown promising clinical benefit in the treatment of advanced NSCLC." (PMID 23861835, 2013). "among known oncogenes, the epidermal growth factor receptor (EGFR) has become the target of different cancer therapies." (PMID 23637683, 2013). "Cytokines and growth factors in conditioned medium obtained from EGFR-TKI-treated cancer cells were analyzed using cytokine membrane array and ELISA." (PMID 23592411, 2013). "Dysregulation of AURKA and EGFR is observed in different types of cancer and is an important indicator of prognosis in cancer development." (PMID 23520446, 2013). "We demonstrate invitro evidence suggesting that IL-6 from cancer cells induces acute interstitial pneumonia as one of mechanisms responsible for the occurrence of a side effect of EGFR-TKI treatment." (PMID 23592411, 2013). "EGFR is one of the most intensely studied and well understood regulators of epithelial cell proliferation, and EGFR inhibitors are, probably, the best examples of mechanism-based anti-cancer drugs." (PMID 23527233, 2013). "This treatment is effective against EGFR-activated cancers, providing an advantage in cancer control of this group." (PMID 23647947, 2013). "EGFR is often overexpressed in cancers, thus inhibition of EGFR-TK as a target for cancer chemotherapy has proven to be effective in both preclinical and clinical settings." (PMID 23494210, 2013). "At least three different types of agent for EGF/EGFR inhibition are currently in use: tyrosine kinase inhibitors (TKIs), monoclonal antibodies (Mabs), and molecular cancer vaccines." (PMID 26317020, 2013). "All of these antigens have been previously cited as biomarkers, potential therapeutic cancer targets or fully validated therapeutic targets, such as EGFR." (PMID 23406016, 2013). "New and more effective methods in blocking EGFR-mediated signal transduction will be helpful in cancer therapy." (PMID 23613900, 2013). "AREG has been reported to be overexpressed in aggressive forms of cancer, and distinct signaling properties have been reported for EGFR and AREG with respect to endocytosis of ligand-receptor complexes, and initiation of downstream signaling." (PMID 23762360, 2013). "Monoclonal antibodies for EGFR, including cetuximab and panitumumab, have been developed for the treatment of multiple cancer types." (PMID 23577026, 2013). "Using cytokine membrane arrays, we screened factors that were up- or down-regulated in Conditioned Medium (CM) obtained from EGFR-TKI- or αEGFR antibody-treated cancer cells." (PMID 23592411, 2013). "On the cancer cells expressing EGFR or EGFRvIII, which absorbed the vectors carrying the reversed coding sequences for the hrDNases, there were no changes of the membranes’ topography." (PMID 24587967, 2013). "EGFR overexpression by cancer cells is indicative of this ligand-receptor complex role in the pathogenesis of GBM." (PMID 24175095, 2013). "Although EGFR levels are elevated in several cancers, its prognostic and therapeutic significance in various cancers are quite variable." (PMID 24354805, 2013). "The main goal at the end is to increase the effectiveness of available EGFR-targeted therapies in advanced cancer patients." (PMID 23637683, 2013). "As an EGFR over-expression cancer, locally advanced NSCLC has been treated with concurrent chemo-radiation with a 5-year survival of approximately 15%, and 5 year loco-regional control of approximately 70% based on major randomized studies." (PMID 24252457, 2013). "Moreover, activating Ras mutations, EGFR overexpression, and phosphorylation of Akt and phosphoinositide-3-kinase have been found as being associated with radioresistance in vitro and, with respect to EGFR and Akt, to the failure of radiotherapy in cancer patients." (PMID 23378947, 2013).
cancer (continued). "Certain EGFR (epidermal growth factor receptor, another tyrosine kinase) driven cancers of breast, lung, pancreas, etc. are sensitive to gefitinib (Iressa) or erlotinib (Tarceva)." (PMID 25825654, 2013). "This analysis identified enrichment of gene sets generally attributed to cancers in patterns associated with HNSCC, including KEGG cancer pathways, ERBB, and MAPK/EGFR signaling pathway activity." (PMID 24223768, 2013). "Recent work showed crosstalk between signaling pathways involving integrins and EGFR in cancer progression." (PMID 23951036, 2013). "After examining the function of HGF by treating cancer tissues with it, which resulted in completely blocked EGFR tyrosine kinase activity." (PMID 23407898, 2013). "Aberrant activation and overexpression of EGFR leads to dysregulation of signaling pathways crucial for cell proliferation, survival, cancer progression, angiogenesis and metastatis." (PMID 24124611, 2013). "Typically, signaling through both EGFR and c-Met promotes cell survival and proliferation and is required by the cancer cells." (PMID 23762292, 2013). "Because IL-6 has been suggested to contribute to the development or progression of acute interstitial pneumonia, we anticipated the possible linkage between IL-6 from cancer cells and EGFR-TKI-induced acute interstitial pneumonia." (PMID 23592411, 2013). "EGFR-mediated signaling involves inflammatory gene expression including cyclooxygenase (COX)-2 and interleukin (IL)-8, and is associated with cancer pathogenesis." (PMID 23774942, 2013). "The epidermal growth factor receptor (EGFR) signaling is one of the most common deregulated pathways in cancer." (PMID 23355974, 2013). "The study reveals that IgA antibodies directed against EGFR and engaging Fcalpha receptor (FcαRI) on effector cells, have in vivo anti-cancer activity." (PMID 23918228, 2013). "The blockade of EGFR and ErbB-2 has been clinically validated as an attractive approach for cancer therapy." (PMID 23936329, 2013). "Gefitinib and erlotinib used in the treatment of certain types of cancer are epidermal growth factor receptor (EGFR) tyrosine kinase inhibitors." (PMID 24089667, 2013). "Because STAT3 is one of the targets for anti-cancer drug resistance, most of investigations have been only focused on how IL-6 regulates the drug resistance in EGFR-TKI-treated cancer cells." (PMID 23592411, 2013). "Both the ErbB2 and the ErbB1 receptors, members of the epidermal growth factor receptor (EGFR) family, are upregulated in many types of cancer, and overexpression of these proteins is associated with a greater likelihood of metastasis." (PMID 23706161, 2013). "Although it has been demonstrated that advantages of EGFR inhibition on radiosensitization of cancer cells is mainly due to a reduction in cell proliferation and clonogenic survival, our results provided new evidence for the importance of EGFR inhibition." (PMID 23951036, 2013). "In aggressive inflammatory breast cancer, inhibition of the EGFR reversed the mesenchymal phenotype of cancer cells to a less aggressive and potentially more chemotherapy-sensitive epithelial phenotype." (PMID 23637683, 2013). "An important characteristic of the diagnosis of CRC is differential high expression of EGFR, proposing these receptors as attractive targets for cancer diagnosis and treatment." (PMID 23857061, 2013). "Shall we conclude that EGFR-targeted therapies have a minor impact on survival in advanced cancer patients?" (PMID 23637683, 2013). "On the other hand, EGFR-TKI activates AP-1 in cancer cells and produces a large amount of IL-6 while growth inhibition is observed." (PMID 23592411, 2013). "Most of cancer tissues are shown to overexpress EGFR, and EGF-EGFR axis has been considered a attractive target for cancer treatment." (PMID 23592411, 2013). "Since EGFR has a key role in cancer, it is important to understand how drugs affect the availability and functionality of EGFR in the cell membrane." (PMID 24349439, 2013).
cancer (continued). "As anti-EGFR strategies, such as cetuximab, are part of a long-term cancer therapy, isolated usage of oral antibiotics seems to be an insufficient approach and has to be seen critically." (PMID 23918349, 2013). "The multiple cell-signalling changes driving resistance and associated disease progression, nevertheless reveal potential cancer cell vulnerabilities for example mTOR, EGFR/HER2 and Src kinase." (PMID 24286369, 2013). "Epidermal growth factor receptor TKIs, such as erlotinib, are commonly utilized as part of cancer therapy." (PMID 23407898, 2013). "Cancers with high EGFR expression demonstrate additional benefit from hyperfractionated radiotherapy regimens." (PMID 24364026, 2013). "MiR-7 also attenuates the activation of Akt and ERK that is induced by EGFR signaling in multiple cancer cell types." (PMID 24349829, 2013). "As one of the crucial cancer pathways, the RTK/ERK pathway is said to be one of the important links in cancer's development, containing a number of genes (EGFR, EGF, CCND1, MAPK3, etc.)." (PMID 24223781, 2013). "On the other hand, all cases were positive for EGFR 1 (EGFR, ErbB1, HER1), and all but one carcinoma with chondroid metaplasia, for cytokeratins 5/6." (PMID 24083491, 2013). "EGFR is involved in invasion and metastasis of several human carcinomas, and correlates directly with CXCR4 expression." (PMID 23472069, 2013). "Validation of EGF-NIR binding properties was performed using monolayers of A431 carcinoma cells expressing high levels of EGFR." (PMID 23857061, 2013). "They found that all carcinomas in which tyrosine phosphorylated PLC-gamma 1 was present also expressed detectable levels of the epidermal growth factor receptor or erbB-2, two tyrosine kinases known to phosphorylate this enzyme." (PMID 23369435, 2013). "Overall, the hazard ratios of cancer death were 3.044 (95% CI: 1.6–5.9) for EGFR and 1.090 (95% CI: 1.0–1.2) for ErbB2 overexpression." (PMID 22991510, 2012). "EGFR is overexpressed or aberrantly activated in various types of human cancer, such as breast, ovarian, and non-small-cell lung carcinoma (NSCLC)." (PMID 22957020, 2012). "Previous publications have noted that EGFR signaling regulates macrophage colony-stimulating factor-1 (MCSF-1) expression in murine cancer cells." (PMID 22276166, 2012). "EGFR overexpression has been demonstrated in many human cancers, including lung, colon, pancreas, breast, ovary, bladder, kidney, and the nervous system." (PMID 22615840, 2012). "Due to their important role in the treatment of cancer, we have developed a cell-level pharmacokinetic/pharmacodynamic model for antibodies antagonistically inhibiting the epidermal growth factor receptor (EGFR)." (PMID 22399130, 2012). "The link of ErbB2/HER2 with cancer is also observed in human, as overexpression of the human ErbB2 gene, which encodes the human EGFR (also known as HER2), is related with cancer." (PMID 23209942, 2012). "In cancer cells, EGFR ligand levels are frequently elevated and EGFR itself is commonly overexpressed." (PMID 23233863, 2012). "The majority of human epithelial cancers are marked by the activation of EGFR, which was the first growth factor receptor to be proposed as a target for cancer therapy." (PMID 22937740, 2012). "Epidermal Growth Factor Receptor (EGFR) and the phosphatidylinositol 3-kinase (PI3K), are oncogenes frequently mutated in human cancers." (PMID 22662165, 2012). "EGFR, FGFRs, PIK3CA, PIK3R1 and AKT1 are proto-oncogenes, frequently activated in cancer through gain-of-function mutations and/or overexpression." (PMID 24213504, 2012). "Several recent studies have indicated that VeriStrat classification has significant power to predict response and survival to EGFR inhibitors for several cancer types." (PMID 22363766, 2012). "The epidermal growth factor receptor (EGFR) is overexpressed and induces proliferation in multiple cancers including pGBM." (PMID 22291938, 2012).
cancer (continued). "The aptamers have been conjugated to gold nanoparticles to specifically deliver these nanoparticles to EGFR-positive cancer cells by receptor-mediated endocytosis." (PMID 22685651, 2012). "Expression of EGFR, Src, integrin αvβ5, and MUC1 are associated with the invasive and metastatic potential of various human cancers." (PMID 22586492, 2012). "In summary, the data indicate that a new approach to target EGFR in cancer is at the juxtamembrane region." (PMID 23166750, 2012). "Our data show that ERβ1 impedes EMT and influences invasion by down-regulating EGFR, which is expressed in basal-like cancers." (PMID 23158001, 2012). "Similar increase in HER3/EGFR dimerization by HER2Mab was also observed in T47D (a low HER2 expressing cancer cell line) and SKBR3 (a high HER2 expressing cancer cell line)." (PMID 23342251, 2012). "This study evaluates the potential utility of a modular nanotransporter (MNT) for enhancing the nuclear delivery and cytotoxicity of the Auger electron emitter 125I in cancer cells that overexpress the epidermal growth factor receptor (EGFR)." (PMID 23107475, 2012). "The anti-EGFR monoclonal antibody panitumumab was shown to increase autophagy via the kinase-independent activity of EGFR in maintaining cancer cell survival." (PMID 23050960, 2012). "Epidermal growth factor receptor (EGFr) has emerged as a central molecular target for modulation during cancer therapy." (PMID 22713695, 2012). "Our data show that MMP-1 can regulate the levels of TGF-α in culture supernatants of the MDA-MB-231-BR and -BR3 cells, which in turns affects activity of EGFR in the cancer cells." (PMID 23217186, 2012). "Epidermal growth factor receptor (EGFR) inhibition has now been well established as an effective treatment for various cancers." (PMID 22997576, 2012). "A variety of modalities for blocking EGFR expression and/or function in cancer cells including anti-EGFR monoclonal antibodies (mAbs) and EGFR tyrosine kinase inhibitors (TKI) have been proven effective, particularly when used in combination." (PMID 22355336, 2012). "The objective of the authors was to obtain a wider spectrum monoclonal antibody capable of affecting ligand dependent proliferation of cancers which require signaling by EGFR or ErbB3 or both receptors simultaneously." (PMID 22889873, 2012). "Further evaluation of [125I]SGMIB-MNT as a targeted radiotherapeutic for EGFR-expressing cancer cells appears warranted." (PMID 23107475, 2012). "Near infrared (NIR) fluorescence imaging of EGFR is well suited to evaluation of oral cavity lesions, given the superficial nature of oral epithelial and submusosal cancers." (PMID 23029451, 2012). "Gene amplification leading to EGFR overexpression is found in several human cancers, most commonly in brain tumours." (PMID 23202898, 2012). "Some of characteristics of the malignant phenotype of CRC are correlated with overexpression and hyper-activation of receptor tyrosine kinases such as epidermal growth factor receptor (EGFR), which make these receptors attractive targets for cancer treatment." (PMID 23144978, 2012). "Due to its role in cancer cell progression and survival, several anti-cancer therapies target EGFR have been approved by the FDA." (PMID 23166750, 2012). "The EGF receptor (EGFR) is perhaps one of the signaling systems that undergo most extensive cross-talk in cancer cells, including HCC cells, being considered as a “signaling hub” where different growth and survival signals converge." (PMID 23285165, 2012). "Data from phase 1 clinical trials in several cancer types have indicated that AV-299 is tolerable and can be combined favorably with EGFR inhibitors such as erlotinib and gefitinib." (PMID 22363766, 2012). "The epidermal growth factor receptor (EGFR) has emerged as a promising therapeutic target because it is overexpressed in a wide range of cancers and plays important roles in cell growth and survival." (PMID 24213322, 2012).